COL6A2 (collagen type VI alpha 2 chain)
Diseases named in the same sentence as COL6A2 in open-access papers (continued):
Sharing a sentence is not in itself a finding about the gene and the disease.
cancer (24 papers, 2014 to 2025). A tumor composed of atypical neoplastic, often pleomorphic cells that invade other tissues. "COL6A2 has also been identified as one of the genes in classifiers distinguishing LUSC from other cancer types." (PMID 39968416, 2025). "For instance, proline hydroxylation on some collagen proteins (e.g., COL6A2) was upregulated in the malignant tumor group." (PMID 40216311, 2025). "Further analysis found that COL6A1 and COL6A2 were relatively highly expressed in all cancer types compared with other COL6A members." (PMID 36167487, 2022). "Collectively, these studies strongly support our observations and indicate that the oncogenic role of COL6A2 across various cancers may involve shared mechanisms, particularly the regulation of EMT." (PMID 41323784, 2025). "Similar to our findings using microarray analysis, FoxO was necessary for the cancer-induced upregulation of Cebpb, Fos, Fbxo31 and Psma2, and was necessary for the cancer-induced downregulation of Col6a2, Myoz3 and Tnc (interaction effect, p < 0.05, AAV9-ev C26 vs. AAV9-d.n.FoxO C26, p < 0.05)." (PMID 25539728, 2014). "Gaviscon formulations also revealed the downregulation of various genes such as COL6A2, DOHH, MEX3D, SBNO2, which have roles in cancer or chronic disease progression." (PMID 39409043, 2024). "In pan-cancer analysis, SHOX2 expression positive correlated with CDKN2C (R = 0.41), COL6A1 (R = 0.35), COL6A2 (R = 0.37), DCHS1 (R = 0.37), MAPK7 (R = 0.34), PRRX1 (R = 0.37), RAB23 (R = 0.36) and RSRC1 (R = 0.36) via GEPIA2." (PMID 37170390, 2023). "This is reasonable considering all genes are involved in related pathways such as Proteoglycans in cancer (ERBB2, TIMP3 and IGF2) and ECM–receptor interaction (COL6A2)." (PMID 38069080, 2023). "Within collagen genes represented in this subset (9/15), we found that all the three main COL6 genes (COL6A1, COL6A2, COL6A3) displayed an increased expression in malignant tumors, with a significant and consistent overexpression in GBM." (PMID 37505240, 2023). "Although the three strands of the collagen VI isoforms (COL6A1, COL6A2 and COL6A3) were more abundant in the cancer matrix compared to the healthy matrix in the irradiated groups, these differences were not significant in our Volcano Plots." (PMID 35897841, 2022). "We further conducted coexpression analysis of COL6A members in pan-cancer, and found that COL6A1, COL6A2 and COL6A3 were highly positively correlated." (PMID 36167487, 2022). "At the same time, multiple collagen-related genes (COL6A2, COL3A1, COL4A1, and COL4A2) in the MSC-2 cluster were upregulated in bone metastases, which is consistent with our observation of IGFBP3, TAGLN, LUM, COL6A1, COL6A2, and COL3A1 in pan-cancer in Fig. (1d)." (PMID 39156727, 2024). "We found a consistent positive correlation between fibroblast proportions and expression of collagen genes belonging to fibril-forming (COL1A2) and microfibrillar (COL6A1, COL6A2 and COL6A3) subfamilies across nine cancer types, the exception being KIRC and LGG." (PMID 36321857, 2022).
myopathies (19 papers, 2010 to 2025). "Finally, the recent reporting of this variant showed that it was linked with a myopathy related to COL6A2." (PMID 39596604, 2024). "For example, case U051 was a patient with myopathy, and a collagen disorder was suspected; three VUSs were identified in the COL6A2 gene." (PMID 30109123, 2018). "In order to determine whether the altered tendon fibrillogenesis reported in animal models of COLVI myopathies is also present in humans, we studied a tendon biopsy and tenocyte cultures of a UCMD patient with compound heterozygous mutations in COL6A2 gene." (PMID 27375477, 2016). "It was determined that the presentation did not fit known cases of COL6A2 myopathies, demoting this to an unlikely genetic diagnosis." (PMID 30109123, 2018). "Although the gold standard for the diagnosis of collagen VI myopathy is sequencing of the COL6A1, COL6A2 and COL6A3 genes, this technique is complicated by both the large size of the three genes (107 coding exons in total) and the high frequency of polymorphisms." (PMID 22075033, 2012). "Our first diagnostic hypothesis was either myopathy or collagen VI pathology, but molecular analysis of the COL6A1, COL6A2, COLA613, RAPSN genes did not reveal any rare or pathogenic variant." (PMID 31614862, 2019).
infection (6 papers, 2015 to 2024). The state of being infected such as from the introduction of a foreign agent such as serum, vaccine, antigenic substance or organism. "Nevertheless, the loss of COL6A2, MMP1, and MMP3 transcription in WT infection compared to Δvhs infection was considerably greater (8- to 15-fold), thereby confirming their vhs-dependent transcriptional downregulation." (PMID 33148793, 2021). "It includes genes related to collagen production and organization (COL6A3, COL6A2, COL6A1, etc.), or matrix metalloproteinases (MMP) involved in extracellular matrix remodelling (MMP7, MMP23B), and previously implicated in infection response." (PMID 26331304, 2015). "In the later stage of infection, focal adhesion pathway was associated with ECM receptor interaction pathway through SPP1, col6a2, COL3A1 and VTN proteins, while focal adhesion pathway linked with leukocyte transendothelial migration pathway by RAC1 and LOC733637." (PMID 32632500, 2020). "COL6A2, localized in the ECM, was detected at all three E. granulosus infection stages; COL6A1 expression increased significantly in the middle and late infection stages." (PMID 39625960, 2024). "Using qRT-PCR, these researchers showed that this reduction was vhs dependent based on two sets of genes that exhibited either high (COL6A2, MMP3, and MMP1) or low (GAPDH, ACTB, and RPLP0) reduction in total RNA levels in WT infection." (PMID 33148793, 2021).
muscular disorders (1 paper, 2010). "It is therefore interesting to postulate that suppression of COL6A2 as a result of up-regulated hsa-miR-29b may be one of the genetic mechanisms underlying muscular disorders and motor impairments frequently observed in individuals with ASD." (PMID 20374639, 2010).
neuromuscular disease (1 paper, 2022). "Moreover, we demonstrated that the nucleotide variant c.1659_1660del in the COL6A2 gene is quite common among healthy asymptomatic carriers of the Ossetian-Digor population in RNOA, which is undoubtedly important in the diagnosis of neuromuscular diseases." (PMID 36292982, 2022).
COL6A2 also shares sentences with these, for which no sentence is quoted: Breast Tumors (2 papers); cervical cancer (2); dilated cardiomyopathy (2); genetic disease (2); keratosis pilaris (2); limb-girdle muscular dystrophy (2); nervous system diseases (2); Obesity (2); osteosarcoma (2); Stickler syndrome (2); adenocarcinoma (1); ameloblastoma (1); Arthritis (1); astrocytomas (1); autoimmune disorders (1); bacterial infections (1); Brugada syndrome (1); CADASIL (1); channelopathies (1); chronic hepatitis B infection (1); clear cell renal cell carcinoma (1); collagenopathies (1); colon carcinoma (1); congenital myopathies (1); connective tissue disorder (1); corneal dystrophies (1); COVID-19 (1); deafness (1); diabetic nephropathy (1); Ehlers-Danlos syndrome (1).
A further 37 diseases each share a sentence with COL6A2 in 1 paper.